SOCS3 (suppressor of cytokine signaling 3)
Diseases named in the same sentence as SOCS3 in open-access papers (continued):
Sharing a sentence is not in itself a finding about the gene and the disease.
tumor (continued). "SOCS3 overexpression or pharmacologic inhibition of JAK1/STAT3 markedly suppressed HIF-2α expression and tumor progression both in vitro and in vivo." (PMID 41874563, 2026). "The FXR agonist obeticholic acid (OCA) induces cell cycle arrest and suppresses tumor cell invasion via STAT3 dephosphorylation and SOCS3 upregulation, concomitant with reduced IL-6/STAT3 signaling and pro-inflammatory cytokine (IL-1β, IL-6) secretion." (PMID 40980688, 2025). "SOCS3 is reported to be a modulator of macrophage, which could drive macrophage inflammatory responses and modulate the efficiency of phagocytic processes, indicating that SOCS3 might affect tumor progression and drug sensitivity through mediate the macrophages and monocytes in GBM." (PMID 41318472, 2025). "Specifically, the expressions of CXCL10, ICMA1, IL18, ITGAL, SOCS3, and TLR3 were higher in tumor tissues compared to their corresponding paracancerous tissues." (PMID 40838069, 2025). "Curcumin was also found to influence epigenetic regulation by inhibiting histone deacetylases (HDACs), leading to increased expression of tumor‐suppressor genes such as SOCS1 and SOCS3." (PMID 40927046, 2025). "Using RT-PCR, the expression levels of PIP, PIAS3, SOCS3, STAT5A, and STAT5B were verified at the level of mRNA isolated from the tumor’s margin (normal) (n = 40), mastopathy (n = 16), and BC tumor tissue (n = 42)." (PMID 40003884, 2025). "Epithelial ovarian cancer cell–derived EVs contain miR-222-3p, which regulates the SOCS3/STAT3 pathway and induces macrophage polarization to the tumor-promoting M2 phenotype." (PMID 40574844, 2025). "This miRNA acts by inhibiting suppressor of cytokine signaling 3 (SOCS3) in macrophages, thereby increasing their pro-tumor activity and enhancing tumor growth and metastasis." (PMID 40691627, 2025). "Conversely, CLU, SOCS3, and genes from the HLA-DRB family were significantly highly expressed in NSTAS tumor cells." (PMID 40786043, 2025). "Tumor-derived exosomes with miR-9 and miR-181a activated JAK/STAT by targeting SOCS3 and PIAS3 to promote MDSCs expansion." (PMID 40443670, 2025). "In endothelial-specific SOCS3 KO mice, pathological angiogenesis is promoted in the OIR model, and tumor volume is increased." (PMID 39790557, 2025). "Between ARGs_High tumour cells and T cells, ITGB2-ICAM1 and TGFB1-TGFBR1 were ligand-receptor pairs with strong regulatory potential, while EDN1, JUNB, SOCS3, VIM and COL1A2 were top genes target to TGFB1." (PMID 40830065, 2025). "The results indicated that CDC73, PSMC2, SOCS3, and ETV4 were substantially upregulated in tumor group than that in control group, whereas PLK2 and LMO7 were substantially downregulated in tumor group than that in control group." (PMID 41318472, 2025). "Of note, in vitro and in vivo studies conducted on SCC models showed that SOCS3 (and SOCS1) forced expression by SOCS3-derived peptide (KIR-ESS, see paragraph 4.1) efficiently suppresses IL-22-induced tumor growth." (PMID 38975347, 2024). "In the tumor immune microenvironment of RCC, IL-6 induces the expression of SOCS3 (suppressor of cytokine signaling-3), a negative regulator of cytokine signaling that promotes tumor cell invasion and metastasis." (PMID 38580797, 2024). "Brassinosteroids, a plant antitoxin, were discovered to suppress PIAS3 and SOCS3 by inhibiting STAT3 signaling, which slowed tumor development." (PMID 37081874, 2023). "Clinical data and genetic models support independent tumor suppressor functions of SOCS1 and SOCS3 in the liver." (PMID 36765862, 2023). "Analysis of the TNMplot database indicated similar expression of METTL7B and RNASE3, downregulation of ITGA9 and SOCS3, and upregulation of CLDN18 in the tumor tissues relative to the adjacent normal tissues." (PMID 37438735, 2023).
tumor (continued). "Using Reactome for pathway enrichment analyses, we observed Trp2Vax and immunotherapy treatment upregulated the IL-12 responsive genes, including ITGB1, SOCS3, IFNG and STAT4 in the tumor-infiltrating CD4+ T cells (with a False Discovery Rate, FDR= 0.0016)." (PMID 36911698, 2023). "SOCS3 is a member of the SOCS family of proteins and has been suggested to function as a tumor suppressor by inhibiting the JAK/STAT signaling pathway." (PMID 37270563, 2023). "These included well-known receptor tyrosine kinase genes (EGFR, TEK and OSMR) that activate MAPK and PI3K signaling pathways, and other tumor-promoter genes (ATP8B2, DAAM1, SLAMF8 and SRGN) as well as tumor-suppressor genes (A2M, DAPK1, RASSF8 and SOCS3)." (PMID 37190308, 2023). "The expression levels of CLDN18 (P = 4.4e-04) were significantly higher in HCC tissues compared to the normal tissues, whereas METTL7B, ITGA9, SOCS3 and RNASE3 were downregulated in the tumor tissues." (PMID 37438735, 2023). "miR-30a increases the differentiation and immunosuppressive activity of MDSCs by targeting SOCS3 and stimulating JAK2/STAT3 signaling, thereby reducing CD8+ T cells infiltration and accelerating tumor progression." (PMID 36569895, 2022). "In differently reactivated genes, SOCS3 and SFRP4 as potential tumor suppressor genes, were noted in PJ-34 and 5-aza-dC treatments, respectively." (PMID 36077707, 2022). "Overall, our data unveils a novel tumor-suppressor role of LINC00893 in PCa by targeting miR-3173-5p and maintaining the expression of SOCS3." (PMID 35818076, 2022). "In this study, the authors deleted the STAT3 negative regulator SOCS3, which resulted in unchecked STAT3 signaling in macrophages but overall anti-tumor effects." (PMID 35406557, 2022). "Furthermore, we performed enrichment analysis of SOCS3 and its functional partners to explore the possible pathogenic mechanism of SOCS3 and found that the JAK/STAT and other signaling pathways were involved in the SOCS3-mediated tumor progression, consistent with existing research results." (PMID 35600392, 2022). "For all these processes induced by MFG-E8, multiple signaling pathways have been identified as important in tumor progression, such as the αvβ3/5 integrin, the PI3K/Akt, and the STAT3/SOCS3 pathways." (PMID 35681775, 2022). "Interestingly, the effect of the tumor-activated versus control SCs on SCLC cell invasiveness was significantly higher, and this was associated with a higher level of expression of several genes, including the STAT3, SOCS3, BCL6, ELF3, IGF2, and IL32 genes, in SCLC cells." (PMID 36551618, 2022). "Tumor immunity infiltration of LGG, LIHC, PAAD, and PRAD were strongly correlated with SOCS3 expression (p<0.01), while GHOL, SKCM, SKC-metastasis, and STAD were relatively weakly correlated with infiltration of the six types of immune cells (p<0.05)." (PMID 35600392, 2022). "But in tumor models, EZH2 inhibits the expression of pro-inflammatory genes and pathways, such as SOCS3, STAT1, STAT3, etc.." (PMID 35432300, 2022). "Insummary, our results suggest a molecular mechanism underlying B[a]P-promoted HCCmetastasis that B[a]P-induced miR-650 downregulates SOCS3, thereby activating JAK andSTAT3 to promote tumor cell motility." (PMID 34450627, 2021). "On the one hand, SOCS3 was one of the most key negative regulating factors of the JAK/STAT signaling pathway; on the other hand, SOCS3 inhibited immune infiltration of tumor microenvironment by reducing the production of inflammatory cytokines." (PMID 34926570, 2021). "miR-9 and miR-181a activated the JAK/STAT signaling pathway via targeting SOCS3 and PIAS3 respectively, resulted in T-cell immunity inhibition and tumor progress." (PMID 34707990, 2021).
tumor (continued). "HDAC5 inhibits suppressor of cytokine signaling 3 (SOCS3), which leads to an increase of C-C motif chemokine ligand 2 (CCL2), recruits CCR2+ macrophages, promotes macrophages to reaggregate into tumor microenvironments, and promotes tumor recurrence." (PMID 34880761, 2021). "In pediatric ALL samples, SOCS3 methylation led to constitutive activation of JAK/STAT3 signaling and enhanced Treg cell expression, which in turn negatively regulated anti-tumor immunity." (PMID 34439155, 2021). "GW4064 also induced G1 cell cycle arrest by inducing p21 and suppressor of cytokine signalling 3 (SOCS3) and reducing phosphorylated STAT3, leading to reduced tumor growth." (PMID 35006466, 2021). "Our results showed that the expression of SOCS3 was decreased in ICC and ECC tumor tissues respectively compared with their corresponding para-tumor tissues." (PMID 32284757, 2020). "By analyzing TCGA data and immunohistochemistry staining of tumor tissue, we found that SPTBN1 and SOCS3 were positively coexpressed in EOC patients." (PMID 32516133, 2020). "The expression of SOCS3, JUNB, and ZFP36 is highly correlated in PCa, and through immunohistochemical analysis we found SOCS3, JUNB, and ZFP36 proteins were mainly expressed in PCa epithelial cells with a small amount in tumor stroma." (PMID 32951005, 2020). "Given the tumor suppressor functions and overlapping mechanisms of action of SOCS1, SOCS3 and PIK3R1, further work is needed to disentangle the highly significant negative correlation between SOCS1/SOCS3 and PIK3R1." (PMID 32807134, 2020). "Overexpression of GAS5 inhibits PDAC cell proliferation, migration and gemcitabine resistance through miR-221/suppressor of cytokine signaling 3 (SOCS3) mediated EMT and tumor CSCs." (PMID 32257946, 2020). "This, along with the role of SOCS3 in promoting insensitivity of malignant cells to cytokine signaling, demonstrates how STAT3 overexpression can shape the tumor microenvironment." (PMID 31684088, 2019). "Our results further support the tumour suppressing role of miR-221 in PCa, since it sensitises PCa cells towards TRAIL by regulating the expression of the oncogenes SOCS3 and PIK3R1." (PMID 31828111, 2019). "After having shown that miR-221 strengthens interferon signalling by regulating SOCS3, augmentation of TRAIL effects constitutes a second tumour suppressive role in PCa." (PMID 31828111, 2019). "This loss of inhibitory function leads to excessive activation of signaling pathways normally regulated by SOCS3, such as STAT3 and FAK, promoting tumor growth." (PMID 31748225, 2019). "We observed upregulations of immune checkpoint molecules IL-10, PD1, TGF-β and inflammatory molecule IFN-γ in tumor tissue while SOCS1 and SOCS3 expressions were found to be comparable to controls." (PMID 30859089, 2019). "In contrast, deletion of SOCS3 in myeloid cells leads to an increased activation of the STAT3 and to differentiation into Gr-1+CD11b+Ly6G+ MDSCs, enhancing tumor growth." (PMID 31480382, 2019). "In the tumor tissues formed by HepG2 cells transfected with si-C1QTNF1-AS1, the expression of miR-221-3p, SOCS3, p-STAT3, c-Myc and MCL-1 was increased, decreased, increased, increased and increased, respectively." (PMID 31222560, 2019). "All above data showed that SOCS3 suppression and sustained activation of STAT3 occurred in e-MDSCs, which were correlated with tumor-derived IL-6." (PMID 30083161, 2018). "We also show that the suppression of SOCS3, including the blockade of IL-6 signaling, can induce TRAIL sensitivity, thus leading to the inhibition of tumor growth in IFN-α-resistant RCC cells." (PMID 30167088, 2018). "We have reported that tocilizumab in combination with anti-RCC drugs can effectively suppress tumor growth in vitro and in vivo through repressing activation of STAT3, Akt and mTOR as well as expression of HIF or SOCS3." (PMID 30167088, 2018).
tumor (continued). "In TAs of (+)-JQ1-treated tumor-bearing mice, STAT3 activatory phosphorylation (p < 0.0001, one-way ANOVA) and expression of the STAT3 target suppressor of cytokine signaling 3 (SOCS3) (p < 0.0001, one-way ANOVA) were significantly reduced." (PMID 29167426, 2017). "Our attempt to inhibit the IL-22 signaling by reinforcing the inhibitory SOCS3 action was supported by our observation that SOCS3 is poorly expressed in the BCC and SCC tumor lesions." (PMID 28445952, 2017). "SOCS3 is an inducible endogenous negative regulator of STAT3, and it is suggested as a tumor suppressor gene." (PMID 27190500, 2016). "In addition, SOCS3 may regulate the movement and migration of tumor cells." (PMID 25695729, 2015). "Accumulating studies support that inhibition of SOCS3 expression promoted STAT3 activation, enhanced hepatic fibrosis, increased proliferation and tumor aggressiveness." (PMID 26416445, 2015). "Taking into account the low expression of SOCS-3 in normal kidney, these findings bring forward SOCS-3 as a tumor promoter in RCC, endowing neoplastic cells with a survival advantage." (PMID 24593195, 2014). "However, there is significant heterogeneity of SOCS gene expression in various types of cancer, including HNSCC, and there is no information on the relevance of the loss of SOCS3 for HNSCC tumor progression or correlation with tumor size and grade of dysplasia." (PMID 23028842, 2012). "Overexpression of SOCS3 by CMV-driven plasmids and siRNA-mediated inhibition of endogenous SOCS3 were used to verify the role of SOCS3 on tumor cell proliferation, viability, invasion and migration in vitro." (PMID 23028842, 2012). "Overall, our results indicate that SOCS3 has a tumor suppressor role in HNSCC, since its expression is reduced early in tumor development; and the overexpression of SOCS3 in HNSCC cell lines reduces proliferation, migration and invasion." (PMID 23028842, 2012). "Our data support a role for SOCS3 as a tumor suppressor gene in HNSCC with relevance on proliferation and invasion processes and suggests that abnormal subcellular localization impairs SOCS3 function in HNSCC cells." (PMID 23028842, 2012). "IL-6, though associated with tumor progression via STAT3 activation, can initiate negative feedback through SOCS3 or STAT3 degradation during acute stress." (PMID 41401147, 2025). "The analysis of the published LLC model dataset strongly pointed to glycolytic reprogramming in AMs from tumor-bearing lungs, but did not allow for the evaluation of their ability to secrete SOCS3 protein within EVs." (PMID 41567211, 2025). "Multiple lines of transcriptomic evidence in tumor-educated THP1 cells point to STAT3 pathway activation, including upregulation of canonical STAT3 targets (SOCS3, CISH, BCL3, JUNB, PIM1) and increased expression of STAT3-activating ligands (IL6, IL11, LIF, OSM) in response to TNBC contact." (PMID 41514627, 2025). "Additionally, SOCS3 interferes with IFN-γ-mediated responses, reducing MHC class I antigen presentation and impairing T cell-mediated tumor recognition." (PMID 40076502, 2025). "Concerning Tumor microenvironment (TME) remodeling, a study reported that CRC metastatic cells release the pro-metastatic miR-181a-5p, which targets the Suppressor of cytokine signaling 3 (SOCS3) gene and activates STAT3-mediated-signaling." (PMID 40862737, 2025). "For example, IL-6 signaling facilitates the progression of pre-neoplastic lesions to malignant forms, and negative feedback by SOCS3 proteins was found to decrease primary tumor growth." (PMID 38141171, 2024). "CCNL1, SOCS3, and HSPA6, which are highly expressed in patients with ccRCC, may promote tumor generation." (PMID 37293297, 2023). "Res and TMZ exert the anti-tumor effects mainly by inhibiting STAT3 signaling, and inhibition of STAT3 signaling might be related to upregulation of PIAS3, SHP1, SHP2, and SOCS3." (PMID 37298405, 2023).
tumor (continued). "Therefore, macrophage polarization can be regulated by activating or inhibiting the SOCS3-regulated JAK/STAT3 pathway, providing new therapeutic targets for inflammation, fibrosis, tumor and other related diseases." (PMID 37081874, 2023). "Furthermore, the protein levels of SOCS3 and E-cadherin were upregulated, while N-cadherin and vimentin were downregulated in PC-3-LINC00893 tumor samples." (PMID 35818076, 2022). "The STAT3 inhibitor SOCS3 was significantly suppressed during tumour development as compared with tissue with mucosal inflammation lacking tumours." (PMID 35793807, 2022). "The interaction between SOCS3 and miRNAs plays a critical role in CRC tumor progression." (PMID 35184640, 2022). "Moreover, the expression of SOCS genes at different tumor stages were analyzed and the results showed that the higher the clinical stage, the lower were the expression levels of SOCS2 and SOCS3 (p < 0.05)." (PMID 34120621, 2021). "We have also not clarified the function of SOCS3 in the tumor microenvironmental and systemic immunity." (PMID 33659045, 2021). "Altogether, these results suggest that EYA2 acts as a tumor suppressor to prevent hepatocarcinogenesis and the malignant phenotype of HCC through the SOCS3-mediated blockade of JAK/STAT signaling, providing a molecular basis for the observed increased aggressiveness in EYA2 loss tumors." (PMID 34044846, 2021). "Due to its role in controlling the activation of the STAT3 oncogene, SOCS3 is typically considered a tumor suppressor protein, although this is not always the case in immune cancers." (PMID 34604264, 2021). "Consistent with previous reports describing tumor-derived EVs, immune checkpoints CD47 and CD274/PD-L1, and key regulators of myeloid differentiation (e.g., TRIB1, SOCS3, STAT3) were upregulated in EwS EV-treated cells compared to control, with TC32 EVs generally eliciting stronger effect." (PMID 34440851, 2021). "Moreover, KMT2D positively regulates the enhancer of the tumor suppressor gene IGFBP5 for melanoma suppression and the enhancers of several tumor suppressor genes (e.g., Socs3, Asxl1 and Arid1A) for lymphoma suppression." (PMID 34194626, 2021). "Thus, results for SOCS3 and ITGB5 verified an anti-inflammatory state; results for SOCS3 and AHSP verified a state of enhanced energy efficiency, and the result for CXCL10 (tumor suppressor) verified a higher defense response in the meditation group." (PMID 33804348, 2021). "Moreover, using hepatocyte-specific EYA2-knockout mice (Eya2−/−), we demonstrated that EYA2 acted as a tumor suppressor in the occurrence and progression of HCC through SOCS3-mediated blockade of JAK/STAT signaling." (PMID 34044846, 2021). "Among the genes that showed a negative correlation with SOCS1 and/or SOCS3, nine genes with high expression in tumor tissues predicted poor prognosis, whereas low expression of PIK3R1 was associated with bad prognosis." (PMID 32807134, 2020). "In addition, factors inducing inflammatory responses, like Peli1, Pgts2, Socs3, and Tnfrsf9, were downregulated, while an inhibitor of the NF-κB pathway (Nfkbie) was upregulated in HIF-1α-KD tumor cells." (PMID 33142239, 2020). "SOCS1 expression was also not significantly affected across tumor grades, whereas SOCS3 expression was significantly reduced with increasing tumor grade." (PMID 32807134, 2020). "By biological experiments, we proved that C1QTNF1-AS1 could regulate miR-221-3p/SOCS3 axis to affect JAK/STAT signaling pathway and then finally change the cell behavior and tumor growth of HCC." (PMID 31222560, 2019). "Furthermore, we showed for the first time that by negatively regulating SOCS3 expression, BRD9 in turn influences activation of the tumor-driver STAT5 pathway, affecting leukemic cell proliferation and survival." (PMID 31000698, 2019).